STAT3 (signal transducer and activator of transcription 3)
Diseases named in the same sentence as STAT3 in open-access papers (continued):
Sharing a sentence is not in itself a finding about the gene and the disease.
Alzheimer disease (59 papers, 2011 to 2026). A progressive, neurodegenerative disease characterized by loss of function and death of nerve cells in several areas of the brain leading to loss of cognitive function such as memory and language. "The signaling of one of the JAKs, TYK2-mediated STAT3, has been implicated in chronic inflammatory diseases, such as cancer and Alzheimer’s disease." (PMID 35563697, 2022). "In neurological disorders like multiple sclerosis, parkinson’s disease (PD), HIV-1-associated dementia (HAD), and alzheimer’s disease, activated astrocytes secrete pro-inflammatory mediators (various cytokines and chemokines) by activating NF-κB and STAT3 pathways, causing cell injury in the brain." (PMID 40443235, 2025). "For example, upregulation of TRPML1 in Alzheimer’s disease (AD) inhibits reactive oxygen species (ROS) generation and mitophagy in AD through the signal transducer and activator of transcription 3 (STAT3) pathway, which is implicated in many aspects of autophagy." (PMID 38156109, 2023). "First, in Alzheimer’s disease (AD), Parkinson’s disease (PD), and Huntington’s disease (HD) models, activation of the STAT3 pathway in astrocytes has been observed." (PMID 40002461, 2025). "Studies have shown that in mice, high amounts of Aβ intensify tyrosine phosphorylation and the transcriptional functioning of Tyrosine Kinase 2 (TYK2), which is related to high phosphorylation of STAT3 in brains with Alzheimer’s disease." (PMID 39861194, 2025). "Another study demonstrated that the inhibition of STAT3 phosphorylation can attenuate learning and memory impairment in animal models of Alzheimer’s disease." (PMID 40143170, 2025). "Alzheimer’s disease is related to a dysfunction in the JAK2/STAT3 pathway, in which nicotinic acetylcholine receptors activate this pathway and lower the Aβ neurotoxicity." (PMID 39861194, 2025). "STAT3’s mechanisms have been confirmed in Alzheimer’s disease (AD) model mice, where inhibiting STAT3 expression improves pathological and behavioral abnormalities." (PMID 39188714, 2024). "STAT3 is also involved in the pathogenesis of amyloid deposits in cerebral amyloid angiopathy (a type of cSVD) and Alzheimer’s disease." (PMID 38811690, 2024). "It has also been reported that PIAS3 reduces the activated form of STAT3, increases the activity of the downstream Nestin/Nrf2/HO‐1 pathway, and inhibits damage in Alzheimer's disease model SH‐SY5Y cells." (PMID 39496070, 2024). "Extracellularly, following binding to the CNTFR/WSX-1/GP130 receptor complex, humanin can induce neuroprotection against mechanisms of Alzheimer’s disease pathology in a neuronal cell line via a STAT3 related mechanism." (PMID 37483601, 2023). "It has been reported that JAK2/STAT3 signaling pathway is involved in the neuroinflammation reaction of stroke and Alzheimer’s disease." (PMID 36873101, 2023). "According to previous studies, Stat3 is involved in the active infiltration of immune cells in tumors and Alzheimer’s disease." (PMID 37511374, 2023). "Recent study showed that resveratrol-selenium nanoparticles reduced the protein expression of p-STAT3 as well as IL-1β levels, and suppressed neuroinflammation in Alzheimer’s disease." (PMID 36873101, 2023). "The participation of STAT3 in neuroinflammation and neurodegeneration (i.e., Alzheimer’s disease) has been confirmed in preclinical studies." (PMID 37762522, 2023). "JAK2 and STAT3 are key proteins in this pathway, playing an important role in multiple CNS pathologies, such as Alzheimer's disease, Parkinson's disease, and cerebral ischemic disorders." (PMID 36627822, 2023). "Previous evidence suggests that NF-κB-activated astrocytes release C3 to aggravate brain damage in Alzheimer’s disease, and STAT3-ablated astrocytes lose the ability to facilitate neuronal regeneration after trauma." (PMID 34645472, 2021). "Astrocytes are activated in a reactive state by STAT3 phosphorylation in 5XFAD mice, an Alzheimer’s disease (AD) animal model." (PMID 34246283, 2021).
Alzheimer disease (continued). "For instance, nanodiamond was indicated to have neuroprotective effect in Alzheimer’s Disease (AD) by modulating NF-κB and STAT3 signaling." (PMID 34454522, 2021). "A report has indicated that age- and disease-dependent deterioration in the Jak2/STAT3 axis plays a critical role in the pathogenesis of Alzheimer's disease." (PMID 33228717, 2020). "STAT3 activation also negatively regulates another common target GSK3β of Alzheimer’s disease and T2DM." (PMID 33150068, 2020). "Phosphorylated STAT3, TNFα, and IL-6 were also downregulated in the presence of anatabine in a transgenic mouse model of Alzheimer’s disease." (PMID 32855621, 2020). "In a mouse model of Alzheimer's disease, we deleted Stat3, a canonical mediator of reactive astrogliosis, specifically in astrocytes." (PMID 30617153, 2019). "Our data suggest that reactive astrogliosis, and specifically Stat3 activation in reactive astrocytes, is an important and pharmacologically addressable target in Alzheimer's disease." (PMID 30617153, 2019). "In Alzheimer's disease and neuroinflammation, microglia express IL10ra and exhibit STAT3 Tyr705 phosphorylation following IL-10 stimulation, indicating IL-10 receptor-dependent STAT3 activation." (PMID 42072370, 2026). "The pathogenesis of Alzheimer’s disease was also related to the inactivation of STAT3, in which its activated/phosphorylated configuration (p-STAT3) had a considerable decline in the hippocampal neurons of patients with the pathology compared to the control group." (PMID 39861194, 2025). "STAT3 plays a critical role in the pathogenesis of neuroinflammation and Alzheimer’s disease." (PMID 38275397, 2024). "Although JAK inhibition can have adverse side effects, strategies to specifically target STAT3 with small molecules have been effective in preclinical models of Alzheimer’s disease and may provide alternatives for reducing GFAP pathology in AxD." (PMID 37048051, 2023). "However, JUN, HDAC1, SP1, and STAT3 are also indispensable in the neuronal apoptosis mechanism of patients with Alzheimer's disease." (PMID 34992508, 2021). "In the present study, the impact of STAT3 inhibition on cognition, cerebrovascular function, amyloid pathology, oxidative stress, and neuroinflammation was studied using in vitro and in vivo models of Alzheimer’s disease (AD)-related pathology." (PMID 34911575, 2021). "JAK2/STAT3 axis targeting is suggested in Alzheimer's disease." (PMID 33585010, 2020). "Importantly, these effects also occurred in Alzheimer's disease model mice treated with a pharmacological Stat3 inhibitor drug." (PMID 30617153, 2019). "In addition, STAT3 was found to be phosphorylated in an IFNAR1-dependent manner in a model of Alzheimer’s disease, identifying STAT3 as a crucial downstream effector of type-1 IFN signaling." (PMID 27022620, 2016). "This study investigates the neuroprotective potential of STAT3 inhibition in reducing oxidative stress-induced neuronal damage and apoptosis, a major factor contributing to the onset and progression of neurodegenerative diseases, including Alzheimer’s disease (AD)." (PMID 39648181, 2024). "In an Alzheimer’s disease model, blocking BDNF/TrkB neurotrophic signaling up-regulated inflammatory factors and activated the JAK2/STAT3 pathway, therefore up-regulating CEBPB." (PMID 35204186, 2022). "However, miR-204 silencing reduces mitochondrial autophagy and ROS production in a murine model of Alzheimer disease via the transient receptor potential mucolipin-1 (TRPML1)-activated signal transducer and activator of transcription 3 (STAT3) pathway." (PMID 35053316, 2022). "In addition, studies have uncovered the molecular interactions between compounds derived from Sanghuangporus and Alzheimer’s disease; within Sanghuangporus, 374 disease-related targets have been identified, including crucial ones such as JAK1, LCK, MAPK1, STAT3, and STAT1." (PMID 39997416, 2025).
Alzheimer disease (continued). "The most statistically significant transcription factors were STAT3 (Signal Transducer and Activator of Transcription 3) involved in focal adhesion, DNMT1 (DNA Methyl Transferase 1), and PPARA (Peroxisome Proliferator-Activated Receptor Alpha) involved in Alzheimer’s disease." (PMID 34836168, 2021).
Autosomal dominant hyper-IgE syndrome (59 papers, 2012 to 2025). 2000 IU/ml), recurring staphylococcal skin abscesses, and recurrent pneumonia with formation of pneumatoceles. "De novo mutations in STAT3 are responsible for most cases of Autosomal Dominant Hyper-IgE Syndrome (AD-HIES), which are primarily caused by loss-of-function (LOF) mutations." (PMID 41212476, 2025). "Most (> 90%) cases of autosomal dominant Hyper-IgE syndrome (AD-HIES) are secondary to a loss-of-function mutation in signal transducer and activator of transcription 3 (STAT3)." (PMID 40884553, 2025). "Patients with autosomal-dominant hyper-IgE syndrome due to STAT3 deficiency are particularly susceptible to acquiring staphylococcal pneumonia associated with lung tissue destruction." (PMID 37982695, 2024). "Autosomal-dominant Hyper-IgE syndrome due to dominant-negative mutations in STAT3 (STAT3-HIES) is one of the key IEI associated with a specific susceptibility to S. aureus infections, particularly in the skin and lung." (PMID 38720948, 2024). "Reduced function of STAT3 in patients with autosomal-dominant hyper-IgE syndrome (STAT3-deficient HIES) increases the susceptibility to S. aureus pneumonia and is also frequently associated with postinfectious lung tissue damage." (PMID 37982695, 2024). "Autosomal dominant hyper IgE syndrome (AD-HIES) is caused by heterozygous germline dominant negative STAT3 (STAT3DN) variants and is characterised by recurrent opportunistic bacterial and fungal infections." (PMID 37116791, 2023). "IL-11 plays a role in bone development accounting for the cranial abnormalities seen in STAT3-associated autosomal dominant HIES." (PMID 38133879, 2023). "Using whole-exome sequencing, the STAT3 (c.1294G>T, p.Val432Leu) missense mutation for the autosomal dominant hyper-IgE syndrome was identified, and omalizumab was prescribed at 300 mg every 2 weeks." (PMID 35602476, 2022). "Autosomal-dominant hyper-IgE syndrome patients carrying STAT3 mutations have lower circulating Tfh cells with B-cell-helping function defects, and STAT3-deficient mice show defective Tfh and GC-B cells." (PMID 35795677, 2022). "Dominant negative mutations in the STAT3 gene account for autosomal dominant hyper-IgE syndrome (AD-HIES)." (PMID 36292796, 2022). "Autosomal dominant hyper-IgE syndrome caused by dominant-negative loss-of-function mutations in signal transducer and activator of transcription factor 3 (STAT3) (STAT3-HIES) is a rare primary immunodeficiency with multisystem pathology." (PMID 33523338, 2021). "Patients and mice harboring STAT3 mutations, which cause autosomal dominant hyper-IgE syndrome (AD-HIES), have been shown to be partially protected from anaphylaxis." (PMID 34542605, 2021). "The same effects were observed in the case of STAT3 in autosomal dominant hyper-IgE syndrome, where destabilizing mutations decreased the half-life of the protein leading to its dysfunction." (PMID 31443196, 2019). "A similar role for STAT3 in human T cells was reported in a cohort of patients suffering from autosomal-dominant hyper-IgE syndrome, which is caused by dominant-negative STAT3 mutations." (PMID 31766350, 2019). "We present the case of a 19-year-old female with a mild form of Autosomal Dominant Hyper IgE syndrome (HIES) associated with a loss-of-function mutation in STAT3." (PMID 31737384, 2019). "In other experiments, PBMCs isolated from healthy donors or from autosomal dominant hyper-IgE syndrome (STAT3 loss-of-function) subjects were cultured with combinations of IL-4 and IL-10." (PMID 31026808, 2018). "Autosomal-dominant hyper-IgE syndrome caused by LOF STAT3 mutation, also known as Job’s syndrome, is characterized by recurrent staphylococcal cold abscesses, pneumonia, and eczema." (PMID 28702025, 2017). "In humans, STAT3 deficiency from dominant negative mutations in the STAT3 gene occur in hyperimmunoglobulin E recurrent infection syndrome (HIES or Job)." (PMID 26464811, 2015).
Autosomal dominant hyper-IgE syndrome (continued). "Patients with autosomal-dominant hyper-IgE syndrome associated with dominant-negative mutations in STAT3 lack Th17 cells, revealing the importance of STAT3-dependent signals in the differentiation and/or expansion of human IL-17-producing cells." (PMID 26770017, 2015). "The case presented is very typical of STAT3 deficient autosomal dominant hyper IgE syndrome (ADHIES)." (PMID 25379309, 2014). "Heterozygous mutations in STAT3 are the major cause of autosomal dominant hyper-IgE syndrome (AD-HIES), a multisystem disease affecting the immune and musculoskeletal systems." (PMID 24600453, 2014). "The role of STAT3 in antibody responses in vivo is further illustrated by the study of patients with STAT3 mutations causing autosomal dominant hyper-IgE syndrome (AD-HIES)." (PMID 23923047, 2013). "One of the most well-studied IEIs associated with the JAK-STAT pathway is autosomal dominant hyper-IgE syndrome (AD-HIES)/STAT3 deficiency, characterized by eczema, eosinophilia, elevated IgE levels, mucocutaneous candidiasis, and connective tissue abnormalities." (PMID 37727514, 2023). "Notably, germline loss-of-function (LOF) STAT3 mutations represent the most common cause of autosomal dominant hyper IgE syndrome (AD-HIES)." (PMID 38203559, 2023). "Autosomal dominant hyper IgE syndrome (HIES) results from a loss of function mutation in STAT3." (PMID 31572360, 2019). "While heterozygous germline inactivating mutations in the signal transducer and activator of transcription 3 (STAT3) with dominant negative effect cause autosomal dominant hyper IgE syndrome, heterozygous gain-of-function (GOF) mutations in STAT3 result in an ALPS-like phenotype." (PMID 31849949, 2019). "Autosomal dominant hyper-IgE syndrome caused by mutations in the transcription factor STAT3 (AD-HIES) is characterized by a collection of immunologic and non-immune features including eczema, recurrent infections, elevated IgE levels, and connective tissue anomalies." (PMID 31069200, 2019). "The essential antibacterial and antifungal functions of Th17 cells were shown in patients with autosomal dominant hyper-IgE syndrome characterized by STAT3 mutations, who had a complete loss of Th17 cells and presented with recurrent staphylococcal skin infections and mucocutaneous candidiasis." (PMID 27560150, 2016). "However, naive CD4 T cells from patients with STAT3 mutations causing autosomal dominant hyper-IgE syndrome (AD-HIES) were recently shown to be unable to acquire B cell help activity when stimulated in the presence of STAT3 activating cytokines." (PMID 23923047, 2013). "The presented molecular mechanism of STAT3-YF activity might also be relevant for the understanding of several dominant-negative STAT3 point mutants which are linked to autosomal-dominant HIES." (PMID 24192293, 2013). "A critical role for STAT3 in IL-21 signaling was also confirmed in patients with autosomal dominant hyper-IgE syndrome (AD-HIES), which is caused by loss-of-function mutations of STAT3." (PMID 26966515, 2016). "Like STAT3-associated HIES, IL6ST loss-of-function variant mosaicism is probably present in some patients with IL6ST autosomal dominant HIES." (PMID 38133879, 2023). "Autosomal dominant HIES (AD-HIES), which is the most common form of this disease, is caused by STAT3 gene mutations." (PMID 35345674, 2022). "Autosomal dominant hyper-IgE syndrome (AD-HIES) is a rare inherited primary immunodeficient disease (PIDs), which is caused by STAT3 gene mutations." (PMID 34805040, 2021). "Patients with autosomal dominant hyper IgE syndrome due to STAT3 dysfunction resulting in impaired Th17 generation, are prone to develop cutaneous and pulmonary S. aureus infections." (PMID 33717122, 2021). "Autosomal dominant hyper-IgE syndrome (AD-HIES), formerly known as Job syndrome, caused by loss of function mutations in STAT3, is associated with impaired Th17 development." (PMID 33613511, 2020).
Autosomal dominant hyper-IgE syndrome (continued). "The link between STAT3 expression and IL-17A and IL-17F production was also demonstrated in humans in the context of autosomal dominant hyper-IgE syndrome (HIES, also called Job’s syndrome)." (PMID 29048384, 2017). "The autosomal dominant hyper IgE syndrome is associated with a missense or in-frame deletions in the SH2 and DNA-binding domains in the STAT3 gene (Signal Transducer and Activator of Transcription 3)." (PMID 25379309, 2014). "This regulatory balance is evident in patients with autosomal dominant hyper-IgE syndrome (AD-HIES, also known as Job syndrome), where STAT3 deficiency due to autosomal dominant mutations results in impaired STAT3 activation, altering cellular responses to IL-21." (PMID 40305224, 2025). "Similarly, bi-allelic mutations in ZNF341, the transcription factor that regulates STAT3, lead to the loss of STAT3 and a phenocopy of AD-HIES/Job syndrome, including CMC with diminished IL-17 responses." (PMID 36986378, 2023). "Using the JAK1/2 inhibitor ruxolitinib, along with cells from patients with STAT3 loss of function (STA3 LOF; autosomal dominant hyper IgE syndrome) we examined the role of JAK/STAT signaling in the hyperproliferation and metabolic dysregulation seen in keloid fibroblasts." (PMID 33662027, 2021). "Autosomal dominant hyper-IgE syndrome is a rare primary immunodeficiency (PID) with multisystem pathology, caused by dominant-negative loss-of-function (LOF) mutations in signal transducer and activator of transcription factor 3 (STAT3) (STAT3-HIES)." (PMID 33523338, 2021). "Moreover, B cells failed to produce GZMB in patients with the autosomal-dominant hyper-IgE syndrome which exhibit heterozygous STAT3 mutations, confirming the unique role of STAT3 in GZMB production." (PMID 35359922, 2022). "In fact, LCLs derived from patients with autosomal dominant hyper-IgE syndrome (AD-HIES), a disease that leads to non-functional STAT3 activity, went lytic at a higher rate than LCLs derived from healthy donors." (PMID 39446925, 2024).